USP25 (ubiquitin specific peptidase 25)
Diseases named in the same sentence as USP25 in open-access papers (continued):
Sharing a sentence is not in itself a finding about the gene and the disease.
cancer (continued). "We further show that the inhibitor of USP25 could destabilize KRAS in cancer cells and was efficacious in blocking tumor xenograft growth in mice." (PMID 40473213, 2025). "Genetic depletion of USP25 expression or pharmacological inhibition of the DUB causes decreases in the expression levels of KRAS (WT or mutants) and in the strength of KRAS downstream signaling, resulting in reduced rates of cancer cell proliferation." (PMID 40473213, 2025). "The USP25 protein plays a crucial role in the development of various types of cancer." (PMID 40607251, 2025). "Considering that reduced infiltration of MDSCs has been reported to correlate with increased sensitivity to immunotherapy efficacy in various cancer types, we sought to test whether overexpression of USP25 augments anti-PD-1 therapy efficacy in HNSCC." (PMID 41326342, 2025). "USP25 is a deubiquitinating enzyme that, by cleaving ubiquitin from target proteins, plays an important role in regulating various physiological and pathological processes, including neurological disorders, inflammation, cancer, and metabolic regulation." (PMID 41321637, 2025). "In addition, bioinformatics analysis revealed a consistent pattern of USP25 downregulation in multiple cancers, suggesting a potential role in the malignant progression of cancers." (PMID 41326342, 2025). "The requirement of USP25 for optimal growth was also evident in other cancer cells." (PMID 40473213, 2025). "In conclusion, our study proposes a mechanistic model that USP25 deubiquitinates and modifies SHLD2 with K63‐linked polyubiquitin chains at the K64 site, thereby promoting NHEJ repair, which in turn decreases chemosensitivity in cancer cells." (PMID 38803048, 2024). "The decisive role of USP28 and USP25 in maintaining elevated cellular levels of different ‘hard to drug’ cancer-promoting proteins has rendered both DUBs highly attractive targets for the development of small-molecule inhibitors against different cancers." (PMID 38816515, 2024). "This peptide may be developed as a potential therapeutic option for treating cancer with high USP25 expression." (PMID 38803048, 2024). "CT1113 can reduce c‐MYC levels and inhibit USP28 and USP25 in various cancer cell lines, resulting in decreased expression of MYC–MAX target genes and increased ubiquitination of substrates like c‐MYC and Tankyrase, thus exhibiting a broad‐spectrum anticancer activity." (PMID 39678489, 2024). "Therefore, this review focuses on the basic biology of USP25 and presents the latest discoveries about roles of USP25 in human diseases, such as infectious diseases, neurological diseases, and cancers." (PMID 34249948, 2021). "Several evidences point to the involvement of USP25 in cancer." (PMID 30478318, 2018). "In addition, USP25 levels were higher in primary cancers than in the adjacent controls (P < 0.0001), whereas USP25 levels were negatively related to the tumor size." (PMID 24997798, 2014). "Small-molecule inhibitors aimed at USP25 may provide a novel approach to cancer treatment." (PMID 41321637, 2025). "USP25 could be a promising target for therapeutic intervention in cancer." (PMID 41321637, 2025). "In addition, several studies have reported the role of USP25 in cancer progression." (PMID 38803048, 2024). "Recently, it has been shown that USP25 directly interacts with tankyrases through its C-terminal tail and promotes their deubiquitination and stabilization, thus regulating Wnt/β-catenin signaling pathway, making an important impact in cell proliferation and human cancer development." (PMID 30478318, 2018). "USP25, a DUB, has emerged as a key regulator in multiple cancers and is frequently downregulated in HNSCC." (PMID 41326342, 2025). "Overall, these findings reveal USP25 as a critical effector of SHLD2 in regulating the NHEJ repair pathway and suggest its potential as a therapeutic target for cancer therapy." (PMID 38803048, 2024).
cancer (continued). "In this study, it is demonstrated that the deubiquitinase USP25 promotes non‐homologous end joining (NHEJ), which in turn contributes to chemoresistance in cancer." (PMID 38803048, 2024). "Recently, however, as the structural similarities and differences between USP25 and its homolog USP28 have become clear, mechanisms of action of USP25 in cancer and other diseases have been gradually revealed." (PMID 34249948, 2021). "Meanwhile, USP25 also suppresses NSCLC progression via enhancing phosphatase and tensin homolog (PTEN) stability in cancer cells, which further indicates the significance/importance of USP52 in NSCLC suppression." (PMID 34533198, 2021). "Consistent with this conclusion, we observed a positive correlation between USP25 and EGFR expression in a panel of cancer types." (PMID 33202887, 2020). "Furthermore, the issue becomes more severe, given that the cancer-promoting activity of USP28 and USP25 will probably be further stimulated by the catalytic hyperactivity arising from mutation of the respective glutamates." (PMID 38816515, 2024). "In this study, we found that USP25 is overexpressed in a subset of cancers, leading to activation of the NHEJ pathway and decreased sensitivity to radiotherapy and chemotherapeutic drugs, USP25 may be a good therapeutic target in clinical application." (PMID 38803048, 2024). "Moreover, among the drugs possessing the ability to target USP28 and then contribute to the inhibition of cancers, both AZ1 and vismodegib target not only USP28 but also USP25." (PMID 36879346, 2023). "As recent reports described USP25 as an oncoprotein in diverse tumor entities, the co-inhibition of USP25 by the current available USP25/USP28 dual specific inhibitors for cancer therapy might, therefore, not be an issue." (PMID 34685632, 2021).
tumor (20 papers, 2014 to 2026). "In particular, the tumor tissues with lymph node metastasis presented the lowest expression levels of USP25, suggesting that USP25 may be involved in HNSCC progression and is associated with metastasis." (PMID 41326342, 2025). "Whether PDAC tumor cells are therapeutically vulnerable to the loss of USP25 in an orthotopic tumor model, which have a greater extent of desmoplasia and angiogenesis, has yet to be explored and warrants further investigation." (PMID 35440539, 2022). "Transwell coculture results revealed that MDSCs cocultured with tumor cells with decreased USP25 expression displayed increased chemotactic activity in vitro, and this effect was abrogated upon treatment with an anti-IL-6 receptor antibody (IL-6R Ab)." (PMID 41326342, 2025). "To demonstrate the role of USP25 in tumor growth in vivo, we established doxycycline (Dox)-inducible shUSP25 (and shNC as control) expressing HCT116 cells." (PMID 40473213, 2025). "The tumor volume was recorded every 3 days and our findings indicated that the tumors in the USP25 overexpression group were significantly smaller than those in the control group." (PMID 41326342, 2025). "Our findings revealed that USP25 expression lower in tumor tissues than in adjacent normal tissues and that this reduced expression is significantly associated with poor prognosis in HNSCC." (PMID 41326342, 2025). "Immunoblotting of the tumor protein extracts showed that in the USP25-depleted tumors KRAS protein levels as well as the phosphorylation levels of MEK and ERK were all downregulated." (PMID 40473213, 2025). "USP25 is a multifunctional deubiquitinase that plays a significant role in tumor biology by modulating critical processes such as cell proliferation, survival, DNA repair, and metastasis." (PMID 41321637, 2025). "The focus of the study design was on the microenvironment associated with HNSCC progression, making it a suitable resource to validate USP25 downregulation across tumor stages." (PMID 41326342, 2025). "We also did not observe a compensation of c-MYC when targeting HIF-1α through USP25, which has previously been linked to HIF activity and shown to be upregulated in a PDAC initiation tumor model with HIF1A deletion." (PMID 35440539, 2022). "In PDAC patient samples we also detected strong IHC staining of SLC2A1 primarily in tumor cells, which was positively correlated with USP25 protein expression." (PMID 35440539, 2022). "The functional significance of DUBs was assayed by a loss-of-function genetic screen in PDAC organoids which identified USP25 as an essential DUB required for PDAC tumor growth and viability." (PMID 35440539, 2022). "Therefore, overexpression of USP25 not only attenuates tumor growth but also potentiates the therapeutic efficacy of ICB in HNSCC by suppressing the recruitment of MDSCs and improving the functionality of CD8+ T cells." (PMID 41326342, 2025). "FC analysis further revealed that the combination of USP25 overexpression and anti-PD-1 therapy markedly reduced the accumulation of MDSCs, but strongly increased the number of tumor-infiltrating functional CD8+ T cells, including Granzyme B+ T cells, IFN-γ+ T cells, and TNF-α+ T cells." (PMID 41326342, 2025). "In addition, USP25 knock-out PDOXs displayed impaired tumor heterogeneity, composed mainly of stroma cells with very few tumor cells." (PMID 35440539, 2022). "USP25 exerts a vital part in human malignant tumor cell proliferation and migration." (PMID 35450028, 2022). "Finally, pharmacological inhibition of USP25 in vitro and in vivo caused PDAC cell death and tumor regression, suggesting that USP25 is a promising therapeutic target in PDAC." (PMID 35440539, 2022). "miR-200c may serve as a tumor suppressor in NSCLC through the inhibition of USP25 expression and may be applied for therapeutic purposes." (PMID 30717818, 2019). "The high USP25 level correlated positively with poor tumor differentiation (P = 0.0002)." (PMID 24997798, 2014).
tumor (continued). "Hence, it appears that miR-200c negatively regulates tumor metastasis in NSCLC patients by targeting USP25." (PMID 24997798, 2014). "To assess the direct effect of aberrant USP25 expression on tumor cells, we established cell lines via lentiviral transduction to stably express doxycycline-induced Flag-USP25 and investigated the effects of USP25 overexpression on the proliferation, migration, and invasion of tumor cells in vitro." (PMID 41326342, 2025). "In addition, the level of USP25 had a significant inverse correlation with tumor size." (PMID 24997798, 2014). "We demonstrated that USP25 is overexpressed in HCC and that USP25 depletion significantly suppresses HCC cell and tumour growth." (PMID 41882191, 2026). "To elucidate the contribution of USP25 to the progression of HNSCC tumors, we constructed a mouse syngeneic tumor model." (PMID 41326342, 2025). "Taken together, these results demonstrate that USP25 is crucial for KRAS signaling and tumor growth." (PMID 40473213, 2025). "PDAC is characterized by a severely hypoxic microenvironment, and USP25 depletion abrogates HIF-1α transcriptional activity and impairs glycolysis, inducing PDAC cell death in the tumor hypoxic core." (PMID 35440539, 2022). "Our findings suggest that the USP25-HIF-1α-glycolytic axis is a specific requirement and potential therapeutic vulnerability for PDAC tumor cells." (PMID 35440539, 2022). "Nevertheless, the oncogenic function of USP25 in SCC remains unexplored and more studies are required to prove the safety of the double inhibition in this tumor entity." (PMID 34685632, 2021). "Next, we investigated the expression levels of USP25 in these patients, the results revealed higher mRNA levels of USP25 were found in NSCLC tissues than non-tumor tissues, correlated with distant metastasis, and advancing stage." (PMID 24997798, 2014). "In addition to demonstrating excellent pharmacokinetic properties and potent anti-tumor effects, another advantage of FT206 is its significantly higher selectivity for USP28 over USP25." (PMID 40240356, 2025). "IHC staining was used to detect the expression levels of CD8, CD11b, and USP25, and the results verified a significant positive correlation between increased USP25 expression and reduced MDSC infiltration as well as increased T-cell infiltration in the tumors of tumor-bearing mice." (PMID 41326342, 2025). "USP25/28 inhibitors CT1073 and CT1113 show broad anti-tumor activity." (PMID 41321637, 2025). "Stable overexpression of USP25 resulted in a considerable decrease in tumor size, but the weight of the mice did not significantly change until the end of the experiment." (PMID 41326342, 2025). "Collectively, these results show that pharmacological inhibition of USP25 leads to reduced HIF-1α activity specifically in PDAC tumor cells, which impairs their survival in the hypoxic tumor microenvironment, and subsequently leads to a reduction in PDAC tumor growth in vivo." (PMID 35440539, 2022). "Our study indicated that USP25 overexpression could systematically restore the immunocompetent TIME by reducing MDSC infiltration and recruiting cytotoxic T cells in HNSCC and could enhance the tumor response to ICB therapy." (PMID 41326342, 2025). "Interestingly, we observed that Usp25 is absent in the surrounding stroma cells, indicating that Usp25 is expressed specifically in tumor cells." (PMID 35440539, 2022). "In addition, we did not detect changes in the transcription factor c-MYC upon USP25 depletion, which has previously been linked to HIF activity and tumor metabolism." (PMID 35440539, 2022). "Interestingly, we observed that USP25 mRNA levels are significantly higher in patients with stronger EGFR expression compared with patients with lower EGFR levels in all the tested tumor types, reinforcing the concept of a functional connection between EGFR and USP25." (PMID 33202887, 2020). "The effect of USP25 on tumor metastasis has not been studied." (PMID 24997798, 2014).
tumor (continued). "The results revealed that overexpression of USP25 sensitized the HNSCC tumors to anti-PD-1 treatment and resulted in lower tumor weights, whereas the tumors in the control group did not respond well to immunotherapy." (PMID 41326342, 2025). "siRNA-mediated USP28 but not USP25 depletion, and USP28 inhibitor treatment, considerably reduced protein levels of Δp63, c-JUN, and c-MYC and impaired growth in human LSCC tumour cells." (PMID 34636321, 2021). "In the Swartling dataset, the expression of USP25 was downregulated in the SHH group compared to non-tumor controls (t = 14.37, p = 3.17 × 10−41), while the expression of USP13 was elevated compared to non-tumor tissues (t = 11.36, p = 1.41 × 10−27)." (PMID 37892185, 2023).
infection (7 papers, 2020 to 2025). The state of being infected such as from the introduction of a foreign agent such as serum, vaccine, antigenic substance or organism. "Although our biochemical data indicate an increase in association in infected cells compared with mock infection, visualization would have enabled analyses of Usp25 distribution in infected cells and the bystander population." (PMID 37683630, 2023). "Usp25 was previously implicated in innate immune signaling in mouse models, where Usp25 deficiency resulted in increased susceptibility to infection." (PMID 37683630, 2023). "Upon infection with an RNA or DNA virus, USP25 associates with TRAF3 and TRAF6 and protects TRAF3 and TRAF6 from virus-induced proteasome-dependent or independent degradation." (PMID 34249948, 2021). "Transcriptomic profiling revealed infection-induced upregulation of DUBs, particularly USP25, USP46, and OTUD7B." (PMID 40899844, 2025). "Because Usp25 inhibited late stages in the viral life cycle, we aimed to determine if this occurred as a consequence of increased innate immune responses to infection." (PMID 37683630, 2023). "USP10 and UCH-L5 showed then a decreased activity while USP25 showed an increased activity at 60 min after infection, which was confirmed by a Western blot analysis." (PMID 37841261, 2023). "Using proteomic analysis of selectively isolated enzymatically active DUBs, we confirmed decreased amounts of active USP10 and UCH-L5, as well as increased amount of active USP25, in cells after infection." (PMID 37841261, 2023). "We revealed that USP10, UCH-L5, and USP25 exhibited higher concentrations in exosomes after infection compared to uninfected control." (PMID 37841261, 2023). "Our data indicate that loss of the Usp25-Erlin1/2 dependent restriction results in increased formation of LC3+ compartments, thereby creating an intracellular environment conducive to infection." (PMID 37683630, 2023). "In contrast, secretion of chemokines such as RANTES, MIP-3α (CCL20), MIP-1β (CCL4), and I-TAC (CXCL11) remained unaltered or moderately upregulated in the Usp25−/− cells upon infection." (PMID 37683630, 2023). "Using this proteomic approach, as well as Western blot immunoassays, we showed unchanged expression on the protein level for USP10, UCH-L5, and USP25 in THP-1 cell lysates after infection." (PMID 37841261, 2023). "In contrast, the abundance of amphisomes and/or autolysosomes was reduced upon infection, more significantly in the Usp25−/− cells, suggesting that IAV inhibits the degradative arm of the autophagosomal pathway to prevent virus clearance." (PMID 37683630, 2023). "We next identified greater amounts of UCH-L5, USP10, and USP25 in THP-1 derived exosomes after F. tularensis FSC200 infection." (PMID 37841261, 2023). "Another infection-related function of USP25 involves the degradation of TRAF3, which induces endotoxin tolerance in macrophages." (PMID 34249948, 2021). "Among others, we identified Usp25, which was activated in an infection-specific manner." (PMID 37683630, 2023). "On the contrary, the amount of active DUB USP25 was increased in the cells 60 min post-infection." (PMID 37841261, 2023). "A modest decrease in Usp25 expression occurred over the course of infection." (PMID 37683630, 2023). "We show increased total activity of deubiquitinating enzymes (DUBs) in human macrophages after infection, while confirm reduced enzymatic activities of two specific DUBs (USP10 and UCH-L5), and demonstrate increased activity of USP25." (PMID 37841261, 2023). "For instance, RNF125, IFI35, NLRC5, USP25, and A20 have been shown to negatively regulate RIG-I-induced antiviral signaling upon pathogen infection." (PMID 33584728, 2020). "Although mitochondrial components (e.g., Tufm) were identified as Usp25 interactors, their expression levels were not appreciably altered in wild-type and Usp25−/− cells or in Usp25WT and Usp25C178S during the course of infection with IAV." (PMID 37683630, 2023).
infection (continued). "In line with the immunoblots, quantification by flow cytometry indicated accumulation of autophagosomes upon infection in both wild-type and Usp25−/− cells, with a significantly higher population of non-degradative autophagosomes in the Usp25−/− cells for both mock and infected cells." (PMID 37683630, 2023). "Although expression of Traf3 and Traf6 moderately suppressed infection, they did not alter the increase in IAV production from Usp25−/− cells." (PMID 37683630, 2023).